MARCKS (myristoylated alanine rich protein kinase C substrate)
Diseases named in the same sentence as MARCKS in open-access papers (continued):
Sharing a sentence is not in itself a finding about the gene and the disease.
lung carcinoma (24 papers, 2014 to 2024). "MARCKS levels are elevated in lung cancer and are associated with increased proliferation, migration and invasiveness." (PMID 37377864, 2023). "We also noticed that smoke-induced phospho-p65 upregulation and IκBα degradation were suppressed in MPS-treated cells, suggesting that high phospho-MARCKS abundance caused by smoke exposure contributes to the activation of NF-κB signaling in lung cancer cells." (PMID 33754052, 2021). "Phospho-MARCKS and phospho-p65 were co-upregulated in smoke-associated lung cancer specimens and tissues with high phospho-p65 levels often had higher levels of phospho-MARCKS." (PMID 33754052, 2021). "Our analyses revealed a positive association between phospho-MARCKS and phospho-p65 in these lung cancer specimens (p = 0.015, Fisher's exact test)." (PMID 33754052, 2021). "From a molecular perspective, we propose a novel signaling axis: the MARCKS/NKAP/p65 regulatory axis in smoke-associated lung cancer." (PMID 33754052, 2021). "Conversely, MARCKS is elevated in highly invasive lung cancer and associated with invasion in leukemia cells." (PMID 29069765, 2017). "In a second study, higher phospho-MARCKS staining was associated with shorter survival in a series of 195 operated lung cancers and associated with EGFR-TKI-based treatment in a series of 52 treated metastatic patients." (PMID 28009981, 2017). "MARCKS has previously been reported to promote invasion in lung cancer via an association with the PI3 Kinase/AKT pathway." (PMID 29069765, 2017). "Consistent with previous findings that MARCKS was associated with metastatic potential in lung cancer and colon cancer cells, we showed here that MARCKS positively regulates fibroblast proliferation and migration." (PMID 27081703, 2016). "Additionally, higher phospho-MARCKS levels found in lung cancer patient tissue and were associated with smoking status as well as higher pack-year." (PMID 33754052, 2021). "Their results demonstrated that the MANS peptide reduces cell migration in vitro and invasiveness of lung cancer cells in vivo, by reducing phosphorylation of MARCKS and AKT/Slug axis." (PMID 39000371, 2024). "It was discovered that smoking cigarettes activates MARCKS in lung cancer cells and the epithelium of the airways." (PMID 39253534, 2024). "In lung cancer, MARCKS phosphorylation is correlated with advanced stage and lymph node metastasis and predicts shorter survival." (PMID 36230850, 2022). "Tobacco smoke-induced phospho-MARCKS upregulates the expression of pro-inflammatory cytokines, causes the epithelial-to-mesenchymal transition and induces stem-like properties in smoke-related lung cancer, which can be reversed by a MARCKS-inhibiting peptide." (PMID 36230850, 2022). "In all, we have demonstrated marked association between phospho-MARCKS and NF-κB activity in smoke-related lung cancer as well as identified MARCKS as a regulator of NF-κB through NKAP." (PMID 33754052, 2021). "Western blots also confirmed that smoke exposure increased MARCKS phosphorylation in less-invasive human lung cancer cell lines (H292 and CL1-0, epithelial-like) and lung epithelial cells (HBE1) in a dose-dependent manner." (PMID 33754052, 2021). "Herein, we aimed to determine the contribution of a signaling protein, myristoylated alanine-rich C kinase substrate (MARCKS), in smoke-mediated lung cancer." (PMID 33754052, 2021). "Analysis of co-expressing phospho-MARCKS and phospho-p65 abundance was achieved by using two sequential tissue slices of lung cancer samples from smokers to ensure that images are properly coregistered." (PMID 33754052, 2021). "Differential gene expression analysis of low invasive and highly invasive lung cancer cells (CL1-0 and CL1-5 respectively) yielded a marked NF-κB molecular signature linked to MARCKS activity in highly invasive cells." (PMID 33754052, 2021). "Simultaneously, co-upregulation of phospho-MARCKS and phospho-p65 was seen in smoke-related lung cancer." (PMID 33754052, 2021).
lung carcinoma (continued). "Taken together, these suggest that MARCKS is activated in response to cigarette smoke and is persistent in lung cancer." (PMID 33754052, 2021). "We also computed the correlation between MARCKS gene and NF-κB signaling gene signature in lung cancer specimens from The Cancer Genome Atlas (TCGA) and normal lung tissues from the Genotype-Tissue Expression (GTEx) databases." (PMID 33754052, 2021). "In summary, we demonstrate a novel mechanism of smoke-related lung cancer malignancy through the MARCKS-NKAP molecular complex in regulating NF-κB signaling." (PMID 33754052, 2021). "In this study, we investigated the role of MARCKS in response to cigarette smoke and its participation in downstream signaling to promote lung cancer malignancy." (PMID 33754052, 2021). "Conversely, targeting of MARCKS phosphorylation with MPS peptide, a specific MARCKS phosphorylation inhibitor, suppressed smoke-mediated NF-κB signaling activity, pro-inflammatory cytokines expression, aggressiveness and stemness of lung cancer cells." (PMID 33754052, 2021). "In a screen of two cohorts of lung cancer patients, we confirmed that phospho-MARCKS is positively correlated with phospho-NF-κB (phospho-p65), and poor survival." (PMID 33754052, 2021). "Given that cigarette smoking is a well-known driver of malignant phenotypes in lung cancer 21, we first determined if exposure to smoke regulates MARCKS protein." (PMID 33754052, 2021). "Previously, the MANS peptide has been shown to inhibit basal lung cancer cell migration and invasion by specifically inhibiting MARCKS Ser-159/163 phosphorylation." (PMID 32033033, 2020). "Higher phospho-MARCKS levels are correlated with shorter overall survival of lung cancer patients, suggesting a key role for MARCKS in lung cancer and a therapeutic strategy for inhibiting PKC activity." (PMID 31784636, 2019). "Application of a 25-amino acid peptide (MANS), identical to the MARCKS N-terminus reduced MARCKS phosphorylation leading to impaired cell migration and reduced metastatic potential in lung cancer cells." (PMID 31058089, 2019). "MARCKS knockdown has previously been shown to decrease the levels of phosphorylated AKT in lung cancer cells." (PMID 29069765, 2017). "In another study, elevated levels of MARCKS and phospho-MARCKS were found in highly invasive lung cancer cell lines and clinical NSCL cancer samples." (PMID 28009981, 2017). "MARCKS was also reported to play a crucial role in potentiating lung cancer cell migration/metastasis." (PMID 27935865, 2017). "In another study, MARCKS, specifically its phosphorylated form, was a key player in potentiating lung cancer cell migration/metastasis, suggesting a potential use of MARCKS-inhibition peptides in the treatment of lung cancer metastasis." (PMID 29295532, 2017). "We previously reported that the use of MANS peptide, which targets the N-terminal myristoylation site in MARCKS, was able to reduce phospho-MARCKS levels in lung cancer." (PMID 26015406, 2015). "Recently, increasing evidence points to phospho-MARCKS as a potential target in cancer progression and our laboratory also discovered its significance in lung cancer." (PMID 26015406, 2015). "Whereas MPS has proven to be highly effective in suppressing the progression of several cancers, MARCKS ED-HIV TAT is particularly potent in sensitizing progressive lung cancer to radiation therapy, and MANS has been shown to efficiently repress metastasis development in the lung and breast cancers." (PMID 33958003, 2021). "Likewise, higher levels of phospho-MARCKS were detected in 66% (n = 45/68) of lung cancer specimens from smokers (right)." (PMID 33754052, 2021). "To examine the clinical relevance of the co-expression of phospho-MARCKS and phospho-p65 in smoke-related lung cancer, we then validated both phospho-MARCKS and phospho-p65 signal abundance in another cohort of lung cancer patients (n = 96) with smoking history." (PMID 33754052, 2021).
lung carcinoma (continued). "Given the clear stratification of patient prognosis, utilization of MARCKS with NF-κB pathway markers, such as phospho-p65, may serve as useful predictors of cancer cell behavior and outcomes in lung cancer." (PMID 33754052, 2021). "We also noticed a higher smoking pack-year in lung cancer patients with high phospho-MARCKS." (PMID 33754052, 2021). "Since MARCKS protein is also abundantly expressed in lung tissue and lung cancer, it may also provide a potential mechanism of resistance to BTZ in lung cancer." (PMID 29184971, 2018). "The role of MARCKS in promoting metastases in colon and lung cancer has recently been demonstrated." (PMID 29069765, 2017). "Furthermore, experimental treatment with a peptide that inhibits MARCKS function reduced lung cancer metastasis in vivo." (PMID 29069765, 2017). "SiRNA knockdown of MARCKS expression in invasive lung cancer cell lines reduced migration." (PMID 24977165, 2014). "For example, PKC-alpha and PKC-delta can phosphorylate and translocate MARCKS from the plasma membrane to the cytoplasm in smoke-related lung cancer, and the binding of MARCKS to calmodulin (CaM) could also result in the translocation of MARCKS to activate the downstream PI3K/AKT/mTOR pathway." (PMID 38755678, 2024). "Moreover, treatment with a MARCKS-inhibiting peptide suppresses lung cancer growth and metastasis in vivo and enhances the sensitivity of erlotinib in lung cancer cells, particularly those tumors with sustained activation of phosphoinositide 3-kinase/AKT signaling." (PMID 36230850, 2022). "Finally, treatment with the MANS peptide impaired cell migration in vitro and the metastatic potential of invasive lung cancer cells in vivo, through coordination of increase of E-cadherin expression, suppression of MARCKS phosphorylation and AKT/SLUG signaling pathway." (PMID 28009981, 2017). "There was already evidence that particles released after smoking activate nuclear factor-kappaB (NF-κB) via myristoylated alanine-rich C kinase substrate (MARCKS) protein, which promotes tumorigenesis and proliferation and survival of lung cancer cells." (PMID 37576883, 2023). "The findings demonstrate that the MANS peptide suppresses MARCKS phosphorylation, to affects the AKT/Slug axis signal pathway, and ultimately decreases lung cancer cell motility, invasion, and metastasis." (PMID 37239989, 2023). "Thus, the MARCKS/NF-κB axis presents itself as a promising biomarker, and targeting of this regulatory axis could be a viable and potential therapeutic strategy for smoke-mediated lung cancer progression." (PMID 33754052, 2021). "Through treatment with 50 μM MPS peptide in lung cancer cells exposed to 20% CSE, we confirmed that MPS peptide had an inhibitory effect on smoke-enhanced MARCKS phosphorylation in both CL1-0 and H292 cells." (PMID 33754052, 2021). "Treatment with a 25-mer peptide targeting the MARCKS phosphorylation site domain (MPS peptide) suppressed tumor growth and metastasis in vivo, reduced levels of phospho-MARCKS and PIP3, and enhanced the sensitivity of lung cancer cells to erlotinib treatment in vitro and in vivo." (PMID 28009981, 2017). "Upregulation of MARCKS, particularly phosphorylated MARCKS (phospho-MARCKS) at the phosphorylation site domain (PSD), has recently emerged as both a biomarker and therapeutic target for lung cancer 11, 13, 15, 17, 19, 20, a malignancy etiologically associated with cigarette smoking." (PMID 33754052, 2021). "Data from Gene Expression Profiling Interactive Analysis (GEPIA) 25 analysis confirmed a significantly positive correlation of MARCKS expression with TNFR, RELA, BCL2A1, CXCL1, RELB or TNF-alpha in lung cancer samples but not in normal lung tissues." (PMID 33754052, 2021).
melanoma (12 papers, 2010 to 2025). A malignant, usually aggressive tumor composed of atypical, neoplastic melanocytes. "There are multiple reports describing the MARCKS protein being associated with invasion in glioblastoma, cholangiocarcinoma, leukemia, melanoma, ovarian cancer, prostate cancer, and inflammatory breast cancer." (PMID 31058089, 2019). "Our study shed light on the previously unknown molecular events associated with WNT5A signaling that regulate MARCKS phosphorylation, which is crucial for melanoma metastasis." (PMID 32033033, 2020). "Despite the fact that these databases are based on mRNA analyses and do not necessarily reflect the actual protein levels, these observations suggest that MARCKS expression could be associated with melanoma progression." (PMID 32033033, 2020). "Protrusions of melanoma cells rich in GAP43, MARCKS, and doublecortin travel through white matter and frequently align with oligodendrocyte processes, which are physical guides for the movement of melanoma cells." (PMID 41463339, 2025). "The overexpression of MARCKS has also been reported in several drug-resistant human melanoma cell lines (HMCLs) and in drug-resistant primary multiple melanoma (MM)." (PMID 35628654, 2022). "Inhibition of MARCKS phosphorylation with a MARCKS-inhibitory peptide abolishes WNT5A-mediated melanoma cell invasion, suggesting that MARCKS is a crucial promoter of metastasis in melanoma and a candidate anti-metastatic target in melanoma patients." (PMID 36230850, 2022). "Contrarily, several research groups have observed that higher expression of MARCKS inhibits cancer development and progression in colorectal cancer, hepatocellular carcinoma, melanoma, and glioma." (PMID 33958003, 2021). "Our observations suggest that the MANS peptide can effectively and specifically reduce the phosphorylation of MARCKS in melanoma cells." (PMID 32033033, 2020). "Our results demonstrate that WNT5A-induced activation of MARCKS is a necessary molecular event that is crucial for the metastatic behavior of melanoma cells." (PMID 32033033, 2020). "The aim of the present study was to investigate a potential downstream regulatory role of the MARCKS protein in WNT5A-mediated invasion of melanoma cells." (PMID 32033033, 2020). "In the present study, we used online melanoma database analyses to demonstrate that MARCKS expression was increased in melanoma tissue and that it was directly associated with melanoma patient survival and melanoma cell invasiveness." (PMID 32033033, 2020). "We investigated A2058 melanoma cells exposed to rWNT5A for any changes in the subcellular localization of MARCKS by confocal microscopy." (PMID 32033033, 2020). "Our observation of a decreased F-actin content at the cell edge suggests that WNT5A signaling by phosphorylating MARCKS interferes with the MARCKS F-actin binding ability and destabilizes the F-actin network at the cell edge to favor melanoma cell invasion." (PMID 32033033, 2020). "Our results showed that both a PKC inhibitor and a ROCK inhibitor inhibited approximately 50% of WNT5A-induced MARCKS phosphorylation in A2058 and A375 melanoma cells compared to the vehicle-stimulated controls." (PMID 32033033, 2020). "The finding that MARCKS expression relates to the progression of melanoma is comparable to that found for WNT5A expression in relation to melanoma progression." (PMID 32033033, 2020). "Taken together, our in silico analyses suggest a possible role for MARCKS in promoting melanoma metastasis and thereby reducing the survival of melanoma patients." (PMID 32033033, 2020). "MARCKS expression was significantly related to melanoma cell invasion, as evidenced by the increased expression levels of MARCKS mRNA in the invasive melanoma cell lines in comparison with those in proliferative melanoma cell lines." (PMID 32033033, 2020). "Previously, the phosphorylation status of the MARCKS protein has only been used as an indicator of WNT5A-mediated PKC activation in melanoma cells." (PMID 32033033, 2020).
melanoma (continued). "To evaluate a possible role of MARCKS in melanoma progression, we first investigated its expression in normal versus melanoma tissue from patients included in the Oncomine database." (PMID 32033033, 2020). "Our results demonstrate that WNT5A-induced phosphorylation of MARCKS is not only an indicator of PKC activity but also a crucial regulator of the metastatic behavior of melanoma and therefore an attractive future antimetastatic target in melanoma patients." (PMID 32033033, 2020). "In this study, we identified MARCKS phosphorylation as a novel WNT5A downstream signal crucial for melanoma cell invasion, a key event in the metastatic process." (PMID 32033033, 2020). "Analyses of melanoma patient databases suggested that similar to WNT5A expression, MARCKS expression appears to be associated with increased metastasis." (PMID 32033033, 2020). "The phosphorylated MARCKS Ser-159/163 levels were reduced by approximately 35% in MANS peptide-treated A2058 melanoma cells compared to cells treated with the RNS control peptide." (PMID 32033033, 2020). "Our study demonstrates multiple novel findings outlining an essential role of MARCKS phosphorylation in WNT5A-induced melanoma cell invasion." (PMID 32033033, 2020). "First, we evaluated the levels of MARCKS phosphorylation at Ser-159/163 and Ser-167/170 sites in different melanoma cell lines via Western blotting approach." (PMID 32033033, 2020). "The WNT5A-mediated increase in total MARCKS expression was statistically significant in A2058 cells after 1 h and in A375 melanoma cells after 3 h of treatment with rWNT5A." (PMID 32033033, 2020). "Most importantly, the presence of the MARCKS phosphorylation inhibitory peptide MANS abolished WNT5A-induced A2058 melanoma cell invasion." (PMID 32033033, 2020). "This approach allowed us to completely abolish WNT5A-induced melanoma cell invasion, thus demonstrating for the first time a crucial role of MARCKS phosphorylation in WNT5A-driven melanoma cell invasion." (PMID 32033033, 2020). "Our Oncomine-based analyses revealed that MARCKS mRNA expression is higher in patient-derived melanoma tissue compared to normal skin tissue samples." (PMID 32033033, 2020). "Paradoxically, in transformed fibroblasts and some distinct highly proliferating melanoma, neuroblastoma, glioma, or colorectal cancer cells, MARCKS is downregulated." (PMID 31058089, 2019). "As a result, several MARCKS are released from the membrane into the cytoplasm to promote actin reorganization, cell motility and metastatic potential of melanoma cells." (PMID 29757215, 2018). "Whereas the role of TNC (tenascin C) and FN1 (fibronectin 1) in melanoma development is well documented, implication of MARCKS, RCN3, BAMBI, PEA3/ETV4 and the FK506 family members FKBP7, FKBP10 and FKBP11 in melanoma progression is unclear." (PMID 27689402, 2016). "In order to identify a possible relationship between MARCKS and miR-200c levels in melanoma, MARCKS levels were investigated in the melanoma cell line panel and normal melanocytes plated on a physiologic collagen matrix." (PMID 20957176, 2010). "Cells that express the fusion construct plated on a thick layer of pliable collagen matrix had a more elongated shape than cells transfected with a GFP control plasmid, further supporting the role of MARCKS in modulating melanoma cellular morphology." (PMID 20957176, 2010). "We show that expression of miR-200c in melanoma cells drives the rounded-amoeboid form of cell migration and MARCKS down-regulation." (PMID 20957176, 2010). "MARCKS is down-regulated in most melanoma lines compared to control melanocytes, demonstrating the opposite relationship to that seen for miR-200c." (PMID 20957176, 2010). "Finally, MARCKS phosphorylation drives motility and invasiveness of melanoma cells of both murine and human origin." (PMID 36230850, 2022). "Furthermore, knockdown of the MARCKS gene or inhibition of MARCKS phosphorylation increased sensitivity to anti-melanoma drugs." (PMID 35628654, 2022).